GIP (gastric inhibitory polypeptide)
Diseases named in the same sentence as GIP in open-access papers (continued):
Sharing a sentence is not in itself a finding about the gene and the disease.
Hyperglycemia (continued). "An explanation may relate to both improved insulin sensitivity and glucose effectiveness observed with exercise, or could be ascribed to a blunted insulin secretion during hyperglycemia, GIP stimulation and arginine stimulation after high volumes of exercise." (PMID 37127822, 2023). "Finally, the insulinotropic effect of GIP dominates during hyperglycemia, while the glucagonotropic effect of GIP seems to be most important during hypoglycemia." (PMID 36289848, 2022). "While the GLP-1 reduces blood glucose by several mechanisms, including stimulating insulin secretion and suppressing glucagon release during hyperglycemia, GIP stimulates insulin release during hyperglycemia, but it also stimulates glucagon release during hypoglycemia." (PMID 36289697, 2022). "For many years it was known that intravenous GIP or GLP-1 administration could normalize hyperglycemia in DM 2 patients." (PMID 35205155, 2022). "Sucralose may also affect taste receptors, thereby increasing the secretion of incretins glucose-dependent insulinotropic polypeptide (GIP) and GIP-1, leading to weight gain, hyperglycemia, hyperleptinemia, and hyperinsulinemia." (PMID 34899613, 2021). "GIP can stimulate glucagon secretion at fasting glycemic, during hypoglycemia, and hyperglycemia." (PMID 35054422, 2021). "Suppression of GIP by pasireotide improved cortisol secretion but produced hyperglycemia." (PMID 31572300, 2019). "Using Youden’s J test, a GIP level of 314 pmol/L could predict hyperglycemia (≥140 mg/dl) with sensitivity of 65% and specificity of 100%." (PMID 30948746, 2019). "- Inhibition of DPP 4 (dipeptidyl peptidase-4), a ubiquitous serine protease responsible for cleaving certain peptides, such as the incretins GLP1 (glucagon-like peptide-1) and GIP (gastric inhibitory polypeptide); their role is to raise the insulin level in the context of hyperglycemia." (PMID 30186157, 2018). "After intraportal infusion of GIP, acute hyperglycemia increased insulin concentrations." (PMID 29673130, 2018). "Whether the effect of GLP‐1 may be potentiated by hyperglycemia and hyperinsulinemia, as is the case for GIP, needs to be studied in additional experiments." (PMID 28174344, 2017). "Therefore, the aim of the present study was to study the effect of GIP with hyperinsulinemia and hyperglycemia on subcutaneous abdominal adipose tissue metabolism in obese subjects with IGT before and after weight loss through caloric restriction." (PMID 27136446, 2016). "The improved insulin sensitivity after weight loss as evidenced by the lower glucose infusion rates we had to apply to induce hyperglycemia may have contributed to the improved vascular effect of GIP." (PMID 27136446, 2016). "This may depend on the improved glucose-insulin homeostasis and lower levels of GIP, because GIP together with hyperinsulinemia and hyperglycemia is strongly involved in lipid regulation in humans." (PMID 27664051, 2016). "Because the magnitude and duration of hyperglycaemia required to attenuate the insulinotropic effect of GIP appears to be relatively modest, future evaluation of the use of incretin-based approaches in the critically ill patient should focus on GLP-1 and its agonists." (PMID 25613747, 2015). "Additionally, hyperglycemia further decreases beta-cell response to GIP because it downregulates its receptor in this cell type." (PMID 25177371, 2014). "In subjects with T2D, the overall effect of GIP seems to be in favor of hyperglycemia." (PMID 22619730, 2012). "Through its dual insulinotropic and glucagonotropic effects on stabilizing glucose levels, GIP could provide a buffer against hyperglycemia when large amounts of glucose are consumed and mitigate reactive hypoglycemia, especially after meals with high fat content." (PMID 39114288, 2024).
Hyperglycemia (continued). "Some authors propose that loss of beta cell GIPR function due to cell stress in T2DM patients may reduce the inhibitory effect of insulin on glucagon secretion, leading to elevated GIP-stimulated glucagon secretion even during hyperglycemia, but this hypothesis is controversial." (PMID 37635984, 2023). "Moreover, human studies evidenced that the GIP receptors was down regulated in adipose tissue in insulin-resistant states, but acute infusion of GIP under hyperinsulinism and hyperglycemia conditions promoted adipose tissue glucose uptake and triglyceride hydrolysis." (PMID 35054422, 2021). "This study indicates in patients with critical illness-associated hyperglycaemia that acute intravenous administration of GIP at pharmacological doses has no insulinotropic activity, does not reduce elevated blood glucose concentrations but does cause a significant postprandial rise in glucagon." (PMID 25613747, 2015). "However, GIP is much less active and its receptor is profoundly decreased under hyperglycemia." (PMID 24302978, 2013). "DPP4/CD26 inhibitors (gliptins) have found application in the treatment of hyperglycaemia since they inhibit the degradation of glucagon-like peptide-1 (GLP-1) and glucose-dependent insulinotropic polypeptide (GIP) hormones." (PMID 39273582, 2024). "Incretin hormones, such as glucose-dependent insulinotropic polypeptide (GIP) and glucagon-like peptide 1 (GLP-1), are responsible for augmenting the insulin-secretory response initiated by hyperglycaemia." (PMID 38337719, 2024). "Some animal studies have found that the expression of GIP (and, to a lesser degree, GLP-1) receptors in pancreatic beta cells is (reversibly) reduced during hyperglycaemia." (PMID 37430117, 2023). "The levels of glucose-dependent insulinotropic polypeptides (GIP) and glucagon-like peptide 1 (GLP-1) (hormones affecting postprandial hyperglycemia) and the ratio of phosphorylated protein kinase B (pAkt) to protein kinase B (Akt) were also tested." (PMID 36142554, 2022). "Very recently, there have been reports in the literature of an effect of dual agonists (GIP/GLP-1) having a positive impact on glycemic control and improving insulin sensitivity, thus reducing complications related to hyperglycemia." (PMID 35205155, 2022). "GIP infusion was found to induce lipolysis, shown as increased plasma NEFA and glycerol concentrations, during stable basal insulin substitution and hyperglycemia in men with type 1 diabetes." (PMID 36010335, 2022). "Decreased TCF7L2 protein levels in T2DM correlated with the downregulation of GIP and GLP-1 receptors (GIP-R and GLP-1R), and impaired β-cell function, lead to fasting and postprandial hyperglycaemia." (PMID 32090124, 2020). "Conversely, during the postprandial period, elevated GIP and GLP-1 levels augment postprandial insulin secretion to prevent hyperglycaemia." (PMID 30662430, 2018). "DPP-4 inhibitors control hyperglycemia by blocking DPP-4 enzyme, which degrade incretin hormones-glucose-dependent insulinotropic polypeptide (GIP) and glucagon-like peptide-18." (PMID 29150631, 2017). "Results indicate that pasireotide-induced hyperglycemia is mediated by a reduction in secretion of insulin and incretin hormones glucagon-like peptide-1 (GLP-1) and gastric inhibitory polypeptide (GIP)." (PMID 23673515, 2013). "GIP as well as GLP-1 is a strong insulinotropic agent, and it has recently been reported that the two incretins have different effects on the insulin secretion, with GIP appearing to be more effective at normoglycemic levels and GLP-1 during hyperglycemia." (PMID 22647249, 2012). "In the present study, insulin secretion following stimulation with glucose, glucose with GIP or GLP-1 and arginine was determined before the onset of hyperglycemia in 10-day-old animals." (PMID 21818396, 2011).
Hyperglycemia (continued). "I.v. infusion of GIP (4 pmol/kg/min for 15 min followed by 2 pmol/kg/min for 45 min) significantly reduced plasma CTX levels under both euglycemic and hyperglycemic conditions, with a more pronounced suppression observed during hyperglycemia." (PMID 41596254, 2026). "Nonetheless, while GIP does not stimulate glucagon secretion in healthy individuals under conditions of hyperglycemia, it stimulates glucagon secretion in hyperglycemic subjects with T2D, and in people with hepatic cirrhosis and hyperglucagonemia." (PMID 40024571, 2025). "We next explored the possibility that treatment of WT mice with mouse [D-Ala2]GIP, a relatively stable GIP analog, could reduce STZ-induced hyperglycemia in a fashion similar to that observed with STZ+DCZ-treated K-GsD mice." (PMID 39436694, 2024). "For example, studies in healthy lean human subjects have shown a decrease in non-esterified fatty acids (NEFA) after exogenous GIP administration, with hyperinsulinemia and slight hyperglycemia." (PMID 38579777, 2024). "In T2DM, GIP has a limited ability to stimulate insulin secretion during hyperglycemia and does not significantly reduce blood glucose concentrations, whereas GLP-1 still significantly regulates blood glucose concentrations in patients with T2DM." (PMID 39598478, 2024). "During hyperglycemia, GIP potentiates glucose-induced insulin secretion without exhibiting a glucagonotropic effect." (PMID 39114288, 2024). "It is possible that the inability of GIP to increase insulin secretion during hyperglycemia is primarily due to the lack of glucose amplification of insulin release in DM 2 patients." (PMID 35205155, 2022). "Dual GIP and GLP-1 receptor co-activation enhances insulin secretion by 20–30% more than the single administration, improves insulin sensitivity, and reduces glucagon secretion, and the reduction in hyperglycemia additionally reduces the resistance to GIP." (PMID 36289848, 2022). "In patients with T2D, the strong β-cell resistance to GIP and a slight resistance to GLP-1 could be secondary to glucotoxicity due to a down regulation of their receptors induced by hyperglycemia." (PMID 33320449, 2021). "Thirdly, GIP’s actions on glycaemia seem to be impaired in conditions of chronic hyperglycaemia, which is the principal reason why GIP analogues have not developed for T2D." (PMID 32436022, 2020). "Glucose-dependent insulinotropic polypeptide (GIP) and glucagon-like peptide-1 (GLP-1) are known incretin peptides secreted from the intestine in response to nutrient ingestion that stimulate insulin secretion together with hyperglycaemia." (PMID 32090124, 2020). "While GLP-1 suppresses glucagon secretion at euglycemia, but not during hypoglycemia, GIP stimulates glucagon secretion at euglycemia, but not during hyperglycemia, being one of the reasons behind the apathy for GIP-based therapies for T2D." (PMID 32823659, 2020). "Dipeptidyl peptidase-4 (DPP-4) inhibitors have been known to improve hyperglycemia in T2D patients by stimulating the incretin effects via suppressing the degradation of incretins, such as glucagon-like peptide-1 (GLP-1) and glucose-dependent insulinotropic polypeptide (GIP)." (PMID 32646003, 2020). "In non-diabetics, GIP stimulates glucagon secretion during hypoglycemia and potentiates insulin secretion during hyperglycemia." (PMID 31443356, 2019). "Glucose-dependent insulinotropic polypeptide (GIP), as well as glucagon-like peptide 1 (GLP-1), are the principal incretins that potentiate insulin secretion from pancreatic β cells and reduce postprandial hyperglycemia." (PMID 31509948, 2019). "Although RBT consumption significantly improved postprandial hyperglycemia, the postprandial GIP response was not affected." (PMID 30302087, 2018).
Hyperglycemia (continued). "Previous non-clinical studies and investigations performed in healthy volunteers has established that GPR119 are able to increase the level of circulating incretins including GLP-1, GIP, and tyrosine-tyrosine peptide (PYY), reducing the hyperglycemia after oral glucose load." (PMID 30283402, 2018). "Increased secretion of cytokines and other counter-regulatory hormones are prominent features of critical illness-associated hyperglycaemia and these cytokines possibly downregulate responsiveness to GIP in the critically ill independent of hyperglycaemia." (PMID 25613747, 2015). "It has been reported that an improved control of hyperglycemia may reverse GIPR expression downregulation and resistance to GIP in Zucker rats." (PMID 26221611, 2015). "By contrast, GLP-1 and GIP are not significantly affected by circulating hyperglycemia in the ferret." (PMID 24594704, 2014). "Although GIP is the primary incretin hormone in healthy individuals and plays a crucial role in incretin effects, its insulin response is significantly reduced in individuals with T2DM who have uncontrolled hyperglycemia, a phenomenon referred to as GIP resistance." (PMID 40012909, 2025). "Particularly, it is unclear whether GIP reduces hypercholesterolemia and atherosclerotic plaque formation independent of its ability to decrease body weight and hyperglycemia." (PMID 37592302, 2023). "Tirazepatide (TZT), a dual glucagon-like peptide-1 (GLP-1)and glucose-dependent insulinotropic polypeptide (GIP) receptor agonist may be effective in managing Covid-19-induced hyperglycemia in diabetic and non-diabetic patients." (PMID 37208555, 2023). "Many authors propose a GIP-stimulated glucagon secretion even during hyperglycemia, but this hypothesis is controversial since in Type 1 diabetes patients without insulin secretion, GIP infusion cannot stimulate glucagon secretion during hyperglycemia." (PMID 37635984, 2023). "Nevertheless, it is still not clear whether our newly designed GLP-1/GIP dual-receptor agonist holds protective effects on myocardial injury induced by hyperglycemia and its probable mechanisms." (PMID 35383532, 2022). "On the contrary, GIP enhances postprandial glucagon response, stimulates glucagon secretion from pancreatic a-cells during a state of hypoglycemia or euglycemia but not during hyperglycemia and stimulates glucagon secretion." (PMID 34577569, 2021). "Hence, GIP may assume greater importance to maintain insulin secretion in obese individuals who have decreased GLP-1 secretion, preventing hyperglycemia." (PMID 33320449, 2021). "The inactivity of GIP in T2DM has been investigated in experimental animal models, and it has been reported that hyperglycemia reduces GIP receptor expression in the beta cells and that treatment of the hyperglycemia restores GIP receptor expression and beta cell responsiveness." (PMID 32459834, 2020). "Interestingly, GIP acts glucagonotropically when administered at euglycemia or hypoglycemia but not during hyperglycemia." (PMID 31443356, 2019). "However, when hyperglycemia is combined with AGEs, beta cells are not able to react to the insults and become insensitive to GIP." (PMID 26221611, 2015). "Therefore, we hypothesized that tirazepatide dual glucagon-like peptide-1 and glucose-dependent insulinotropic polypeptide (GIP) receptor agonists might effectively manage Covid-19-induced hyperglycemia in diabetic and non-diabetic patients." (PMID 37208555, 2023). "Moreover, in contrast to GLP-1, GIP has a glucagonotropic action in humans, which, however, depends on the prevailing glucose concentrations: glucagon secretion is increased by GIP in the presence of euglycemia or hypoglycemia but not in the presence of hyperglycemia." (PMID 33419065, 2021). "The first isolated incretin hormone was GIP; however, it was not used as a therapy for T2DM because its function was not fully understood in the state of hyperglycemia." (PMID 36289848, 2022).
Hyperglycemia (continued). "The actions of GLP-1 and GIP on glucagon secretion are different, since GLP-1 suppresses glucagon during hyperglycemia, but not at a normal fasting plasma glucose concentration." (PMID 35054422, 2021). "Pre-meal exercise did not alter insulin-, GIP- and HOMA-IR- lowering effects of low-carbohydrate diet, but exacerbated evening hyperglycemia." (PMID 27798656, 2016). "Tirazepatide (TZT), a dual glucagon like peptide-1 (GLP-1)and glucose-dependent insulinotropic polypeptide (GIP) receptor agonist, may be effective in the management of Covid-19-induced hyperglycemia in diabetic and non-diabetic patients." (PMID 37208555, 2023).
Hypoglycemia (49 papers, 2014 to 2026). A decreased concentration of glucose in the blood. "4.People with CKD who are treated with GLP-1 RAs or GLP-1 RA/GIP RA dual agonists need to only perform regular self-monitoring of blood glucose when they are also being treated with drugs that can cause hypoglycemia (sulfonylureas and insulins) (Grade 1A)." (PMID 41141497, 2025). "2.Other agents within the class of GLP-1 RA or GLP-1 RA /GIP RA dual agonists can be used for the improvement of glycemic control with a low risk of both hypoglycemia and beneficial effects of weight loss in obese people with T2DM and CKD (Grade 1A)." (PMID 41141497, 2025). "There was only one study which found that a greater postprandial peak in GIP was associated with a lower risk of hypoglycaemia." (PMID 37439960, 2023). "Combined with the fact that the role of GLP1 and GIP is itself glucose dependent, the inherent risk of treating hypoglycemia with DPP4i is particularly low." (PMID 35630534, 2022). "GIP acts as a physiological blood glucose stabilizer associated with stimulation of insulin and glucagon secretion during hyper- and hypoglycemia, respectively, in healthy subjects and in patients with T2D." (PMID 29941634, 2018). "When combined with Glucose-dependent insulinotropic polypeptide (GIP) receptor agonists (GLP-1/GIP RAs), these agents exert complementary islet effects and often promote greater weight loss, all with a substantially lower risk of hypoglycaemia than sulfonylureas." (PMID 41262822, 2025). "Thus, GIP′s role in improving glucagon counter-regulation may further contribute to reducing the risk of hypoglycemia associated with DPP4i." (PMID 35630534, 2022). "An increase in heart rate of ∽10 bpm is also observed after GIP infusion in people with T1D clamped either at hyper- or hypoglycemia, along with a decrease in diastolic blood pressure of ∽5 mmHg and an increase in systolic blood pressure of ∽6 mmHg." (PMID 40024571, 2025). "In the postprandial state, GIP stimulates insulin after a meal and glucagon secretion during eu- and hypoglycaemia." (PMID 40218856, 2025). "For example, GIP stimulates glucagon secretion from pancreatic α-cells in hypoglycemia in healthy persons but, in T2D, the glucagonotropic function of GIP is dysregulated." (PMID 39594592, 2024). "Both GLP-1 and GIP can stimulate pancreatic beta cells to secrete insulin in a glucose-dependent manner to control blood glucose levels with hypoglycemia occurring very rarely as an adverse effect." (PMID 35252271, 2022). "Dipeptidyl peptidase IV inhibitors (DPP-4i) prevent the degradation of glucose-dependent insulinotropic polypeptide (GIP) as well as glucagon-like peptide 1 (GLP-1), and are now widely used for the treatment of the T2DM due to the low risk of hypoglycemia." (PMID 36860286, 2021). "A potential additional advantage of GIP is the protection against hypoglycemia since GIP infusion is accompanied by a decreased need for further glucose administration to maintain a satisfactory glycemic level during an insulin-induced hypoglycemic clamp." (PMID 34819089, 2021). "The physiological relevance of GIP-stimulated glucagon during hypoglycemia is unclear, since GIP is secreted in response to nutrients and is expected to be at low levels during hypoglycemia." (PMID 32964214, 2020). "When eating only meat, GIP presumably allows the insulin levels to rise enough to store the fat and protein and the glucagon levels to rise enough to prevent hypoglycemia." (PMID 31781045, 2019). "Another important aspect of the insulinotropic effects of GIP and GLP-1 is their synergy with the sulfonylurea drugs, which is clinically relevant due to the risk of hypoglycemia when used in combined therapies." (PMID 26075286, 2015).